TMEM126A (transmembrane protein 126A)
Description:
Protein required for the cotranslational protein quality control in the inner membrane of the mitochondria. Associates with newly synthesized polypeptides and may act as a chaperone that cooperates with OXA1L for the insertion of newly synthesized mitochondrial proteins into the inner membrane. Required for the assembly of the ND4 module of mitochondrial complex I.
Synonyms: DKFZp586C1924; OPA7
Tractability: Antibody: UniProt predicts a signal peptide or a membrane-spanning region; its Gene Ontology location is reachable by antibodies, with medium confidence. PROTAC: ubiquitination databases record sites on it; its protein half-life has been measured.
Gene: Protein-coding gene on chromosome 11 (85,647,956 to 85,656,547, forward strand). Ensembl gene ENSG00000171202.
Subcellular location: Mitochondrion inner membrane
Subcellular location (Human Protein Atlas): Cytosol; Nucleoplasm
Pathways (Reactome):
Metabolism: Complex I biogenesis
Gene Ontology:
Biological process: mitochondrial protein quality control; mitochondrial respiratory chain complex I assembly; optic nerve development; protein insertion into mitochondrial inner membrane from matrix
Cellular component: mitochondrial inner membrane; mitochondrion; plasma membrane
Genetic constraint (gnomAD): Loss-of-function variants: 6 observed, 14.12 expected, observed/expected ratio (o/e) 0.42, 90% interval 0.23 to 0.84. The upper end of that interval is the gene's LOEUF score, 0.84, which puts it in group 3 of 6, group 1 being the genes least tolerant of losing a copy. Missense variants: 206 observed, 199.83 expected, observed/expected ratio (o/e) 1.03, 90% interval 0.92 to 1.16. Synonymous variants: 59 observed, 70.26 expected, observed/expected ratio (o/e) 0.84, 90% interval 0.68 to 1.04.
Gene-disease validity (ClinGen):
ClinGen rates the evidence that TMEM126A causes each of these diseases.
autosomal recessive optic atrophy, OPA7 type (autosomal recessive): Definitive. An optic atrophy that is caused by a mutation in the TMEM126A gene.
mitochondrial disease (autosomal recessive): Definitive.
Homologues: Orthologues: chimpanzee TMEM126A (100% identical), macaque TMEM126A (92% identical), dog TMEM126A (81% identical), rabbit TMEM126A (78% identical), pig TMEM126A (77% identical), guinea pig TMEM126A (75% identical), mouse Tmem126a (71% identical), rat Tmem126a (69% identical), tropical clawed frog tmem126a (49% identical), zebrafish tmem126a (41% identical), Drosophila melanogaster CG13392 (19% identical). Paralogues in human: TMEM126B (28% identical).
Diseases named in the same sentence as TMEM126A in open-access papers:
TMEM126A is named in the same sentence as 18 diseases in open-access papers, as found by Europe PMC text mining. Sharing a sentence is not in itself a finding about the gene and the disease. The quoted sentences say what the papers report.
optic atrophy (12 papers, 2010 to 2025). A disorder characterized by loss of optic nerve fibers. "The same TMEM126A nonsense variant was further identified in an Algerian consanguineous family with optic atrophy and auditory neuropathy and a Moroccan consanguineous family with isolated optic atrophy." (PMID 35551639, 2022). "A series of studies have confirmed that auditory neuropathy is a key feature of TMEM126A-associated optic atrophy." (PMID 34394341, 2021). "OPA3 mutations result in optic atrophy associated with cataract, while TMEM126A mutations are responsible for an autosomal recessive form of optic atrophy." (PMID 23401657, 2013). "In another Algerian family, affected patients bearing the homozygous p.Arg55X mutation in TMEM126A presented with optic atrophy associated with auditory neuropathy." (PMID 22815638, 2012). "We describe the first detailed phenotyping of patients with autosomal recessive TMEM126A-associated optic atrophy and auditory neuropathy." (PMID 20405026, 2010). "Concerning OPA7, a severe juvenile-onset optic atrophy with central scotoma was found in a large multiplex inbred Algerian family and subsequently in three other Maghreb families with the same mutation in the TMEM126A gene, suggesting a founder effect." (PMID 22776096, 2012). "The clinical phenotype associated with TMEM126A mutations could therefore expand further as more families with syndromal optic atrophy are screened for this particular gene." (PMID 21112411, 2011). "Our findings suggest that auditory neuropathy may be a key feature of TMEM126A-associated optic atrophy." (PMID 20405026, 2010). "The causative variants in PTPN23, TMEM126A, NBAS, and WFS1 genes were identified in 4 probands with a recessive form of optic atrophy." (PMID 36071901, 2022). "(2009) identified mutations in TMEM126A (11q14.1-q21, OMIM 612989) in a large, inbred, Algerian family segregating pure optic atrophy." (PMID 21112411, 2011). "Our findings suggest that a diagnosis of autosomal recessive TMEM126A-associated optic atrophy and auditory neuropathy (ARTOAN) should be considered in patients with optic atrophy and deafness." (PMID 20405026, 2010). "Among the cases of recessive optic atrophy, there was one case of short stature, optic nerve atrophy, Pelger-Huet anomaly (SOPH syndrome) caused by NBAS variants, one case of PTPN23 optic atrophy syndrome, one case of TMEM126A optic atrophy, and one case of Wolfram syndrome." (PMID 36071901, 2022). "Based on this, the patient's clinical diagnosis was revised to TMEM126A optic atrophy." (PMID 36071901, 2022). "Therefore, we expect more cases with TMEM126A optic atrophy to be discovered among East Asian patients." (PMID 36071901, 2022). "The possibility of pathogenic variants within the TMEM126B paralog, TMEM126A, was excluded in subject 6 by analysis of the WES dataset; moreover, optic atrophy is a discriminatory feature in cases of TMEM126A pathology, and this individual has normal visual acuity." (PMID 27374774, 2016). "Notably, our case is the very first case of TMEM126A optic atrophy reported in East Asian patients." (PMID 36071901, 2022). "In addition, TMEM126A might be an important candidate gene to screen in patients with isolated nonsyndromic optic atrophy, especially in juvenile forms and in patients of Maghrebian origin." (PMID 22815638, 2012).
autosomal recessive optic atrophy (6 papers, 2010 to 2023). A rare hereditary optic atrophy characterized by an early onset of bilateral optic nerve degeneration without other systemic features. "TMEM126A was located in the interval, and a mutation of this gene was reported in autosomal recessive optic atrophy during the course of our study." (PMID 22815638, 2012). "Interestingly, the TMEM126A gene that was recently described in association with autosomal recessive optic atrophy was located within this candidate interval." (PMID 20405026, 2010). "TMEM126A is a gene that encodes an assembly factor for the ND4-module of mitochondrial complex I, in which variants of this gene cause non-syndromic autosomal-recessive optic atrophy." (PMID 36071901, 2022).
auditory neuropathy (4 papers, 2010 to 2021). A hearing disorder characterized by impaired transmission of signals through the auditory nerve, resulting in mild to severe hearing loss and poor speech perception. "Furthermore, patients with homozygous TMEM126A mutations should be investigated for subclinical evidence of auditory neuropathy." (PMID 20405026, 2010). "In addition, as the same mutation was recently identified in two siblings with arOA and auditory neuropathy, originating from a consanguineous Maghreb family, which prompted the authors to postulate that TMEM126A could also be expressed in inner hair cells." (PMID 22815638, 2012).
breast carcinoma (2 papers, 2019). "In particular, the loss of TMEM126A promotes cell adhesion and migration in breast cancer cells via ECM remodelling and EMT induced by mitochondrial ROS overproduction." (PMID 31052256, 2019). "Moreover, both in vitro and in vivo invasive breast cancer cells show a loss of transmembrane protein 126A (TMEM126A), mitochondrial retrograde signaling alterations, EMT induction, and altered extracellular matrix composition." (PMID 31027222, 2019). "The transmembrane protein 126A (TMEM126A) is a mitochondrial transmembrane protein that is anchored to the inner membrane close to the cristae, which is downregulated in highly metastatic breast cancer cells." (PMID 31052256, 2019).
cognitive decline (1 paper, 2025). "In the meantime, EA improved cognitive decline, possibly targeted at the transmembrane protein 126A (TMEM126A) and the excitatory amino acid transporters (SLC1A2/EAAT2) in rats with neuropathic pain." (PMID 38379403, 2025).
heart failure (1 paper, 2024). Inability of the heart to pump blood at an adequate rate to meet tissue metabolic requirements. "We could show that genes important for ATP biosynthesis and electron transport (e.g., PGAM2, NDUFA1, and TMEM126A) are consistently downregulated in heart failure." (PMID 38573186, 2024).
TMEM126A also shares sentences with these, for which no sentence is quoted: autosomal dominant optic atrophy (2 papers); Optic neuropathy (2); Wolfram syndrome (2); Behr syndrome (1); Cognitive impairment (1); Costeff syndrome (1); deafness (1); hearing defect (1); hypertrophic cardiomyopathy (1); mitochondrial disease (1); Pelger-Huet anomaly (1); SOPH syndrome (1).